GAN (gigaxonin)
Description:
Probable cytoskeletal component that directly or indirectly plays an important role in neurofilament architecture. May act as a substrate-specific adapter of an E3 ubiquitin-protein ligase complex which mediates the ubiquitination and subsequent proteasomal degradation of target proteins. Controls degradation of TBCB. Controls degradation of MAP1B and MAP1S, and is critical for neuronal maintenance and survival.
Synonyms: GAN1; KLHL16; GIG
Tractability: Small molecule: it has a binding pocket of medium quality; it belongs to a druggable protein family. PROTAC: UniProt records ubiquitination sites on it; ubiquitination databases record sites on it; its protein half-life has been measured.
Gene: Protein-coding gene on chromosome 16 (81,314,944 to 81,390,884, forward strand). Ensembl gene ENSG00000261609.
Subcellular location: Cytoplasm; Cytoplasm, cytoskeleton
Subcellular location (Human Protein Atlas): Microtubules
Pathways (Reactome):
Immune System: Antigen processing: Ubiquitination & Proteasome degradation
Metabolism of proteins: Neddylation
Gene Ontology:
Molecular function: protein binding; ubiquitin-like ligase-substrate adaptor activity
Biological process: protein ubiquitination; proteasome-mediated ubiquitin-dependent protein catabolic process; cytoskeleton organization
Cellular component: Cul3-RING ubiquitin ligase complex; cytoplasm; microtubule cytoskeleton; cytosol; cytoskeleton
Genetic constraint (gnomAD): Loss-of-function variants: 30 observed, 48.3 expected, observed/expected ratio (o/e) 0.62, 90% interval 0.46 to 0.84. The synonymous counts are far from expectation, so gnomAD's model fits this gene poorly and the ratio says little. Missense variants: 723 observed, 588.77 expected, observed/expected ratio (o/e) 1.23, 90% interval 1.15 to 1.31. Synonymous variants: 315 observed, 219.05 expected, observed/expected ratio (o/e) 1.44, 90% interval 1.31 to 1.58.
Gene-disease validity (ClinGen):
ClinGen rates the evidence that GAN causes each of these diseases.
giant axonal neuropathy 1 (autosomal recessive): Definitive.
Homologues: Orthologues: macaque GAN (100% identical), pig GAN (98% identical), guinea pig GAN (98% identical), mouse Gan (98% identical), rat Gan (98% identical), rabbit GAN (98% identical), chimpanzee GAN (96% identical), dog GAN (86% identical), tropical clawed frog gan (84% identical), zebrafish GAN (60% identical). Paralogues in human: KLHL2 (27% identical), KLHL3 (27% identical), KLHL1 (26% identical), KLHL14 (26% identical), KLHL28 (26% identical), KLHL5 (26% identical), IPP (25% identical), KEAP1 (25% identical), KLHL17 (25% identical), KLHL20 (25% identical), KLHL4 (25% identical), KLHL26 (25% identical), and 42 more.
Diseases named in the same sentence as GAN in open-access papers:
GAN is named in the same sentence as 28 diseases in open-access papers, as found by Europe PMC text mining. Sharing a sentence is not in itself a finding about the gene and the disease. The quoted sentences say what the papers report.
giant axonal neuropathy (17 papers, 2009 to 2025). A rare inherited disorder affecting the neurofilaments. "Giant axonal neuropathy is a rare autosomal recessive neurodegenerative disease caused by mutations in the GAN gene." (PMID 32158379, 2020). "Second, several mutations in the KREP domain of the BTB-Kelch protein Gigaxonin, which cause giant axonal neuropathy in humans, were shown to decrease Gigaxonin protein abundance through altered stability, as evidenced by pulse chase experiments." (PMID 31337835, 2019). "Mutations in the gene Gan, which encodes gigaxonin, can cause an autosomal recessive sensorimotor disease, called giant axonal neuropathy, but a specific function for skeletal muscle has not been reported yet." (PMID 27707793, 2016). "However, the patient was still ambulant at the age 12, demonstrating that distinct clinical signs of classical and mild giant axonal neuropathy can sometimes overlap, and suggesting a similar loss-of-function mechanism for GAN missense and nonsense mutations." (PMID 39680150, 2024). "Indeed, recessive mutations in the Gigaxonin-encoding gene cause Giant Axonal Neuropathy (GAN), a severe neurodegenerative disorder characterized by a wide disorganization of the Intermediate Filament network." (PMID 24758703, 2014). "The mammalian BTB-Kelch gene gigaxonin is mutated in giant axonal neuropathy, a severe autosomal recessive sensorimotor neuropathy affecting both the peripheral nerves and the central nervous system and is characterized by cytoskeletal neurofilament disorganization." (PMID 19859546, 2009). "KLHL16 (or GAN) is the gene that encodes gigaxonin, and it is mutated in the pediatric neurodegenerative disease Giant Axonal Neuropathy (GAN)." (PMID 40161598, 2025). "Giant Axonal Neuropathy (GAN) is a neurodegenerative disease caused by loss-of-function mutations in the KLHL16 gene, encoding the cytoskeleton regulator gigaxonin." (PMID 39282431, 2024). "Giant axonal neuropathy, for example, is due to defects in gigaxonin that maintains neuroaxonal cytoskeletal integrity and transport, but is also responsible for proper intermediate filament degradation in astrocytes." (PMID 28638987, 2017). "Mutations in GAN (KLHL16), or gigaxonin, are linked to human giant axonal neuropathy, an autosomal recessive disorder." (PMID 23676014, 2013). "Gigaxonin is encoded by the KLHL16 gene, which is mutated in Giant Axonal Neuropathy (GAN)." (PMID 40161598, 2025). "Giant axonal neuropathy (GAN) is a progressive neurodegenerative disease affecting the peripheral and central nervous system and is caused by bi-allelic variants in the GAN gene, leading to loss of functional gigaxonin protein." (PMID 39680150, 2024). "Giant Axonal Neuropathy (GAN) is a pediatric neurodegenerative disease caused by loss-of-function mutations in the E3 ubiquitin ligase adaptor gigaxonin, which is encoded by the KLHL16 gene." (PMID 36393840, 2022). "Moreover, mutations in different E3 ubiquitin ligase genes have been identified in several neurodegenerative diseases, such as Sacsin in the autosomal recessive spastic ataxia of Charlevoix-Saguenay, Gigaxonin in Giant axonal neuropathy and Malin in Lafora disease." (PMID 24312598, 2013).
Sensorimotor neuropathy (4 papers, 2009 to 2024). "Homozygous and compound heterozygous mutations in the GAN gene are consistent with the Giant axonal neuropathy type 1, which is an autosomal recessive sensorimotor neuropathy." (PMID 36866531, 2023). "Mutations in the GAN gene cause loss of function of gigaxonin, a cytoskeletal regulatory protein, clinically leading to progressive sensorimotor neuropathy, reduced coordination, slurred speech, seizures, and progressive respiratory failure leading to death." (PMID 30966479, 2018).
cognitive deficits (2 papers, 2020 to 2023). "A patient with very rare inherited neuropathy (giant axonopathy, gigaxonin gene) revealed also nerve enlargement, whereas those patients without neuropathy (one with diffuse pain syndrome and one with cognitive deficits) revealed normal nerve values." (PMID 32411079, 2020).
axonal neuropathy (1 paper, 2007). Any nerve disorder affecting the axon of a nerve. "These include the NRM (nurim [nuclear envelope membrane protein]), ZDHHC19 (zinc finger, DHHC-type containing 19), UCP2 (uncoupling protein 2 [mitochondrial, proton carrier]) and GAN (giant axonal neuropathy [gigaxonin]) genes." (PMID 17974019, 2007).
Hepatic failure (1 paper, 2023). "On the other hand, liver cirrhosis, fatty liver, and hepatic failure phenotypes were associated with variants in NAB1, CALD1, ZBTB16, GAN, TEMD3, and/or PRDM15 genes." (PMID 37664632, 2023).
sensory ataxia (1 paper, 2020). Any ataxia in which the causes of the disease is a perturbation of the sensory system, leading to its dysfunction. "Another 10-year-old girl harboring two pathogenic variants in a compound heterozygous manner in the GAN gene [c.805C>T (p.Arg269Trp)]; [c.732delT (p.Ile244MetfsX33)] showed wide based, high steppage gait with sensory ataxia with positive Rhomberg’s signs." (PMID 32999401, 2020).
neurodegenerative disease (8 papers, 2013 to 2025). A disorder of the central nervous system characterized by gradual and progressive loss of neural tissue and neurologic function. "Giant axonal neuropathy (GAN) is a progressive neurodegenerative disease caused by recessive mutations in the GAN gene encoding the ubiquitously expressed protein gigaxonin, whose main function is to facilitate degradation of intermediate filament proteins." (PMID 35008700, 2021). "Recent studies have confirmed that gigaxonin E3 ligase regulates ATG16L1 ubiquitination, affecting autophagy in neurodegenerative diseases." (PMID 38994020, 2024).
cancer (7 papers, 2020 to 2024). A tumor composed of atypical neoplastic, often pleomorphic cells that invade other tissues. "KLHL members associated with inherited forms of the human disease include KLHL3, KLHL7, KLHL9, KLHL12, and GAN (KLHL16), whereas KLHL6, KEAP1 (KLHL19), KLHL20, and ENC1 (KLHL37) are associated with cancer." (PMID 33897412, 2021). "They believe that GAN expression could be the biomarker of cancer." (PMID 33329727, 2020). "However, ASB2 and HECW2; DET1, GAN, and HERW2 were expressed minimally in the LAML and DLBC cancers, respectively." (PMID 35711821, 2022).
tumor (3 papers, 2021 to 2024). "Of these, DHRS3, DUSP4, GAN, RGS12, and TRIM14 are known oncogenes or tumor suppressors (as indicated by CancerMine)." (PMID 33849068, 2021).
autosomal recessive disease (1 paper, 2025). Autosomal recessive form of disease. "This childhood-onset autosomal recessive disease is caused by loss-of-function mutations in gigaxonin, the E3 adaptor protein that enables neurofilament degradation." (PMID 40059823, 2025).
infection (1 paper, 2018). The state of being infected such as from the introduction of a foreign agent such as serum, vaccine, antigenic substance or organism. "Previous experiments in a mouse burn wound model infection are in line with this observation, given that much lower GaM concentrations were needed to prevent P. aeruginosa and A. baumannii proliferation, compared with GaN." (PMID 30250828, 2018).
GAN also shares sentences with these, for which no sentence is quoted: amyotrophic lateral sclerosis (2 papers); lung carcinoma (2); non-small cell lung carcinoma (2); Anxiety (1); Ataxia (1); autosomal recessive spastic ataxia (1); chronic lung infection (1); congenital nemaline myopathies (1); cystic fibrosis (1); Lafora disease (1); liver cirrhosis (1); lung adenocarcinoma (1); neurodevelopmental disorder (1); neuropathy (1); Parkinson's (1); polyneuropathy (1); Sensory neuropathy (1).